IL6 (interleukin 6)
Diseases named in the same sentence as IL6 in open-access papers (continued):
Sharing a sentence is not in itself a finding about the gene and the disease.
mood disorder (continued). "Leptin is involved in neuroimmune interactions that link obesity, inflammation, and mood disorders, as it stimulates the release of proinflammatory cytokines such as IL-6, TNF-α, and IFN-γ, which are well-established activators of IDO1, thereby increasing the degradation of Trp through the KP." (PMID 41516008, 2025). "Elevated levels of pro-inflammatory cytokines such as IL-6, TNF-α, and C-reactive protein (CRP) are commonly observed in individuals with inflammatory depression and have been linked to increased vulnerability to mood disorders." (PMID 41162174, 2025). "The similarity in IL-6, Zn, CRP, and albumin levels between UD and BD during depressive episodes of similar severity suggests common underlying pathophysiological processes in mood disorders." (PMID 38785543, 2024). "Inflammatory markers and pro-inflammatory cytokines, including tumor necrosis factor-alpha and interleukin-6 may also potentiate mood disorders." (PMID 36275825, 2022). "Findings from previous research showed that an imbalance between pro- and anti-inflammatory cytokines demonstrated through a higher ratio of TNF-α/IL-10 and IL-6/IL-10 in the brain of animals exposed to chronic mild stress, may contribute to mood disorders." (PMID 33810574, 2021). "Overall, we demonstrate that blood IL-6, GDNF and BDNF could be informative peripheral biomarkers of brain biology associated with mood disorders, substance disorders, and suicide." (PMID 34078872, 2021). "Although IL-6 seems to be reliably activated by mental stress and to play an important role in mood disorders, other cytokines including TNF-α, IL-1ra and IL-1β appear to be relevant in the association of sedentary behaviour and mood but were not assessed in this study." (PMID 26294364, 2016). "Interestingly, among the 52 differentially regulated transcripts were genes encoding proteins associated with intracellular pathways associated with the development of mood disorders, MAPK and IL-6 signaling." (PMID 27188165, 2016). "The divergent findings related to IL-6 levels in mood disorders in the literature may be a consequence of differences in the methods and samples used." (PMID 23497121, 2013). "The pro-inflammatory cytokine interleukin-6 (IL-6) is involved in the regulation of several physiological processes, particularly in the immune response, as well as in sleep regulation, metabolism, and mood disorders." (PMID 23497121, 2013). "Indeed, preclinical and clinical studies have repeatedly demonstrated that an increase in the expression and activation of this inflammasome induces a higher release of cytokines, such as TNF-α, IL-1β, and IL-6, which have been shown to be elevated in individuals with this mood disorder." (PMID 36613574, 2022). "Mood disorders are accompanied by chronic systemic inflammation and increased plasma levels of pro‐inflammatory cytokines such as tumor necrosis factor‐alpha (TNF‐α) and interleukin‐6 (IL‐6)." (PMID 37933420, 2023). "As IL-6 signals via the JAK/STAT pathway, jakinibs may prove to be a useful tool in mood disorders, greatly widening the scope of jakinib indications." (PMID 35056105, 2021). "Finally, the significant allelic ratio variation of SLA-DRB1 in the amygdala, combined with its known importance in regulating pro-inflammatory cytokines (e.g., IL-1β, IL-6, TNF-α) and microglial activation, supports its involvement in immune regulation and stress-related mood disorders." (PMID 40969342, 2025).
polycystic ovary syndrome (65 papers, 2011 to 2026). A disorder that manifests as multiple cysts on the ovaries. "It is inferred that the single nucleotide polymorphism in IL6 is a genetic cause of polycystic ovary syndrome." (PMID 33623786, 2021). "Metformin treatment of patients with polycystic ovary syndrome is associated with lower serum IL-6 levels." (PMID 28202017, 2017). "BMI, polycystic ovaries, and specific metabolic markers emerged as key predictors, underscoring the multifaceted role of IL-6 in the pathophysiology of PCOS." (PMID 40226143, 2025). "SGD has demonstrated anti-inflammatory effects in other models, including reduction of IL-1β and IL-6 in polycystic ovary syndrome." (PMID 41446282, 2025). "Several studies have reported significantly elevated levels of pro-inflammatory cytokines (e.g., IFN-γ, IL-2, TNF-α, IL-6, and IL-23) within the follicular fluid of patients with polycystic ovary syndrome." (PMID 40813502, 2025). "Apigenin treatment reduced the production of the inflammatory cytokines tumor necrosis factor-α (TNF-α) and interleukin-6 (IL-6) in the blood of rats with polycystic ovarian syndrome." (PMID 39457717, 2024). "on polycystic ovary syndrome-induced mice, LC in the dosage of 500 mg/kg for every second day demonstrated a significant reduction in IL-6, MDA, and tumor necrosis factor- α (TNF-α) in the intervention group versus control after 28 days." (PMID 38444016, 2024). "It has been revealed that there is a strong connection between inflammation and polycystic ovary syndrome in which high levels of C-reactive protein are considered a sign of evoked inflammatory response, along with other inflammatory cytokines, such as IL-6." (PMID 38397957, 2024). "Increased plasma concentrations of inflammatory markers, including TNF-α and Interleukin 6 (IL-6), have been shown, for example, in polycystic ovary syndrome." (PMID 37762666, 2023). "Polycystic ovary syndrome patients reportedly exhibit lower serum IL-6 levels and improved chronic inflammation during early use of metformin." (PMID 34603199, 2021). "This study showed that curcumin via inhibition of TNF-α and IL-6, by reducing the follicular sheath, improving ovulation and corpus luteum, will improve histologic features of polycystic ovary and will push it towards having active and healthy ovary." (PMID 29201665, 2017). "Regarding chronic low-grade inflammation in polycystic ovary syndrome, most of the articles in the literature have revolved around C-reactive protein, an acute-phase protein produced by the liver in response to interleukin-6 and tumor necrosis factor stimulation." (PMID 38397957, 2024). "High amounts of interleukin 6 (IL-6) may also promote adrenal steroidogenesis and contribute to hyperandrogenemia." (PMID 37854752, 2023). "Interleukin-6 (IL-6) is an inflammatory cytokine predominantly secreted by adipocytes and plays a key role in the pathophysiology of polycystic ovary syndrome (PCOS)." (PMID 39691364, 2024). "Studies have indicated that individuals with polycystic ovary syndrome exhibit elevated levels of inflammatory markers such as TNF, IL-6, CRP, IL-18, IL-1β, and white blood cell counts." (PMID 40933264, 2025). "Coptis chinensis, an important medicinal plant in the Ranunculaceae family, has been found to reverse the pathological damage of ovarian tissue in polycystic ovary syndrome and regulate the mRNA and protein expression levels of MAPK1, CXCL8, IL-6 and IL-1β." (PMID 40842497, 2025). "Moreover, some miRNAs, such as miR-021, miR-27b, miR-103, and miR-155, have been linked to IR and polycystic ovary syndrome (PCOS) indirectly through inflammatory pathways such as tumor necrosis factor (TNF) and interleukin-6 (IL6)." (PMID 37108651, 2023). "In mouse models of polycystic ovary syndrome, treatment with DHEA resulted in increased production of cytokines such as serum TNFα, IL-6, IL12p70, and IFNγ." (PMID 37268990, 2023).
polycystic ovary syndrome (continued). "In polycystic ovary syndrome, C1QTNF6 upregulates serum levels of proinflammatory factors, such as C-reactive protein (CRP), interleukin 6 (IL-6), and tumor necrosis factor-α (TNF-α)." (PMID 36052307, 2022). "Likewise, in polycystic ovary syndrome (PCOS), IL-6 levels are higher than in matched controls and a positive correlation between high circulating IL-6 levels and androgen status was described." (PMID 33362560, 2020). "This study aimed at investigating the therapeutic effects of curcumin on IL-6, CRP and TNF-α and symptoms of polycystic ovary syndrome." (PMID 29201665, 2017). "Insulin resistance is linked to the buildup of visceral adipose tissue, which potentiates proinflammatory cytokines and adipokines, including IL-6, TNF-α, and leptin, enhancing lipolysis and stimulating the ovaries to produce androgens, leading to hyperandrogenemia." (PMID 39064282, 2024). "Additionally, an increase in the serum levels of IL-6 and TNF-α was observed in polycystic ovary syndrome." (PMID 39495423, 2024). "Increased levels of the inflammatory cytokines Il-6 (interleukin-6), Il-18 (interleukin-18), TNF-alpha (tumor necrosis factor alpha), hsCRP (high-sensitivity C-reactive protein) and ferritin are present in patients with polycystic ovary syndrome." (PMID 37509592, 2023). "ROS: Reactive oxygen species, IL-6: Interleukin-6, PAI: Plasminogen activator inhibitor, IL-8: Interleukin-8, POF: Premature ovarian failure, PCOS: Polycystic ovary syndrome." (PMID 38970048, 2024). "Having low-grade chronic inflammation such as elevated C-reactive protein (CRP), interleukin-6 (IL-6) and tumor necrosis factor-α (TNF-α) plays a crucial role in polycystic ovary syndrome (PCOS)." (PMID 29201665, 2017). "IL-6 is a typical immune response regulatory factor and its expression is closely related to levels of OS damage in cells or tissues, regardless of premature ovarian failure (POF), polycystic ovarian syndrome (PCOS), or ovarian damage caused by environmental pollutants." (PMID 33521822, 2021). "PCOS, polycystic ovary syndrome; 17-OHP, 17-hydroxyprogesterone; FSH, follicle stimulating hormone; LH, luteinizing hormone; TNF-α, tumor necrosis factor-α; IL-6, interleukin-6." (PMID 32187268, 2020). "Rimonabant treatment for 12 weeks in obese women with polycystic ovarian syndrome resulted in increased circulating levels of VEGF however, the treatment did not alter TNF-α, IL-1β, IL-2, and IL-6, which is in contrast to our results following AM251 treatment." (PMID 36232744, 2022).
prediabetes (65 papers, 2014 to 2026). "Elevated levels of IL-18, NFATC4, TNF-α, and IL-6 were all associated with significantly higher odds of prediabetes compared to healthy controls (all P < 0.001)." (PMID 40027364, 2024). "The association of increased lean mass with decreased muscle IL-6 was significantly stronger in prediabetes (Fisher r-to-z P = 0.0004)." (PMID 30587230, 2018). "Perhaps most interestingly, the association of reduced muscle IL-6 with improved body composition was greater in prediabetes than RA." (PMID 30587230, 2018). "Chronic hyperglycaemia associated with prediabetes and T2DM stimulates the release of inflammatory cytokines such as CRP and IL-6." (PMID 41296388, 2025). "Elevated IL-18, IL-6, and TNF-α levels were associated with significantly increased prediabetes odds in univariate analysis (all P < 0.001)." (PMID 40027364, 2024). "IL-18, IL-6, and TNF-α were selected as the focus of this study due to their strong association with the chronic inflammation underlying prediabetes and its progression to cardiovascular disease." (PMID 40027364, 2024). "It was found that higher levels of inflammatory markers (IL-18, TNF-α, IL-6) and increased NFATC4 gene expression were associated with a greater risk of prediabetes compared to healthy controls." (PMID 40027364, 2024). "The concentrations of proinflammatory molecules such as IL-6, IL-1β and IL-8 were increased in the T2D and prediabetes groups compared with the control group." (PMID 38834984, 2024). "The prediabetes stage is associated with an increased level of inflammatory markers, namely, CRP, IL-6, and TNF-α." (PMID 38068801, 2023). "In the prediabetes group, IL-1β, IL-6, IL-8, TNF-α and MAPK were significantly higher in those with Vit D insufficiency and deficiency groups." (PMID 38136648, 2023). "This was in partial agreement with previous results, where IL-6 levels were higher in both prediabetes and T2DM than controls." (PMID 37383391, 2023). "Adiponectin levels in the subgroups of prediabetes patients with HOMA-IR >2.8 were found to be strongly correlated with IL-6 (R = 0.6663, P = 0.005) or TNF-α (R = 0.7732, P < 0.001), but in the other three subgroups, there was no such correlation." (PMID 35311231, 2022). "Studies have shown that people with prediabetes have an increase in several inflammatory markers, such as resistin, interleukin 6 (IL-6), TNF-α, interleukin 1β (IL-1β), and monocyte chemoattractant protein-1 (MCP-1), in their serum and fasting glucose levels." (PMID 36582230, 2022). "Serum IL-6 levels in T2DM or prediabetes were dramatically increased in contrast to the healthy, while no significant variation was displayed between the prediabetes and T2DM." (PMID 35311231, 2022). "For similar reasons, the TNF-α and IL-6 levels were significantly higher in the PICF of the prediabetes group." (PMID 36557041, 2022). "In the splinted crown subgroup of prediabetes, the value of IL-6 was 154 pg/mL and that of TNF-α was 115 pg/mL." (PMID 36557041, 2022). "As for IL-6, our study detected remarkably increased IL-6 levels in prediabetes in contrast to those in healthy and that levels insignificantly dropped when compared to those in T2DM." (PMID 35311231, 2022). "TNF-α and nesfatin-1 levels in T2DM were obviously different compared to prediabetes or the healthy; IL-6 and adiponectin levels in the healthy group were significantly changed in contrast to prediabetes or T2DM." (PMID 35311231, 2022). "The immune system molecules, particularly interleukin (IL)-6 and IL-10, are other important molecules that mediate the inflammatory response and need more study in prediabetes." (PMID 34099024, 2021). "Prediabetes stage is associated with the increase in the level of inflammatory markers, that is, CRP, IL-6 and TNF-α." (PMID 33211181, 2021).
prediabetes (continued). "Cytokines play an important role in the procedure of β-cell failure and IL-1β; TNF-α and IL-6 have been shown to diversely regulate pancreatic β-cell function leading to inflammation in prediabetes patients." (PMID 30039349, 2019). "H3K4me3 was enriched at the promoter of E2F1, LPL, SREBF2, SCD1, PPARG and IL6 in lean normoglycemic compared to morbid obese subjects with prediabetes." (PMID 30958852, 2019). "Several population-based studies have confirmed that low-grade systemic inflammation and increased levels of markers of inflammation such as hs-CRP, IL-6, tumor necrosis factor-α, and IL-1RA are already present in those with prediabetes." (PMID 28911155, 2017). "Interestingly, exenatide treatment in humans living with prediabetes also acutely induced IL-6 secretion by monocytes and increased systemic IL-6 levels." (PMID 40892365, 2025). "Additionally, the prediabetes and T2D groups had higher concentrations of proinflammatory molecules such as IL-6, IL-1β and IL-8, and lower concentrations of IL-10, an anti-inflammatory cytokine, than controls (P < 0.001)." (PMID 38834984, 2024). "The Health, Aging, and Body Composition study demonstrated that dysglycemia is associated with inflammation, as expressed by an increase in CRP, tumor necrosis factor-alpha (TNF-a), and interleukin-6 (IL-6) levels among older people (70–79 years) with prediabetes and DM." (PMID 39335474, 2024). "However, the levels of the proinflammatory interleukins IL-6, IL-1b and IL-8 were increased in the T2D and prediabetes groups compared with the control group." (PMID 38834984, 2024). "Research indicates that individuals with prediabetes exhibit elevated levels of multiple inflammatory markers, including resistin, interleukin-6 (IL-6), TNF-α, interleukin-1β (IL-1β), and monocyte chemoattractant protein-1 (MCP-1), in their serum along with high fasting blood glucose levels." (PMID 39634176, 2024). "IL-6 levels slightly decreased moving from controls to prediabetes, then exhibited a rise in T2DM." (PMID 37383391, 2023). "Additionally, a recent study reported that physical activity with or without dietary or lifestyle modification reduced the levels of IL-6 in individuals with prediabetes." (PMID 38004306, 2023). "However, vitamin D3 supplementation tends to decrease the ratio of IL-6/IL-10 compared with the prediabetes group." (PMID 37324274, 2023). "However, the variation of TNF-α and IL-6 levels in prediabetes and their comparison with T2DM and the healthy group have not been disclosed." (PMID 35311231, 2022). "Nonetheless, previous studies suggested that pro-inflammatory diet could promote low-grade inflammation that is characterized by elevated pro-inflammatory markers, namely, CRP, TNF-α, and interleukin-6 which may lead to prediabetes and IR." (PMID 35250879, 2022). "Among Danes, individuals with prediabetes had significantly (Wilcoxon test, padj < 0.05) higher levels of interleukin 6 (IL6), tumor necrosis factor α (TNFα), lipopolysaccharide-binding protein (LBP), and intestinal alkaline phosphatase (IAP) compared to normoglycemic individuals." (PMID 33658065, 2021). "This study hypothesized that opioid peptides and their receptors combined with the immune cytokines (IL-6 and IL-10) affected the IR parameters in prediabetes patients." (PMID 34099024, 2021). "In the first comparison, the physical activity intervention administered along with or without dietary or lifestyle modification may reduce the level of leptin and IL-6 in individuals with prediabetes." (PMID 33211181, 2021). "In addition to the excess body adiposity found in the study participants, they had prediabetes and higher cytokine level, which was observed by increased glycated hemoglobin levels (A1c) and IL-6, respectively." (PMID 34501915, 2021).